IL5 (interleukin 5)
Diseases named in the same sentence as IL5 in open-access papers (continued):
Sharing a sentence is not in itself a finding about the gene and the disease.
asthma (continued). "Compared with OVA sensitization or hyperoxia exposure alone, the mice in the model group (O2+OVA) showed asthma-like symptoms and increased airway hyperreactivity,The levels of IL-5,IL-13 IL-17A were increased in BLAF,and total leukocyte and eosinophil counts were also significant increasesed." (PMID 38148813, 2024). "Additionally, a study conducted with asthma patients also demonstrated decreased IL-5 and IL-13 levels with omalizumab treatment, further supporting this theory." (PMID 38795119, 2024). "As asthma is the overwhelming indication for these anti-IL5 drugs, we assumed the suspect observations could represent the safety concerns indicated for asthma as well." (PMID 38308249, 2024). "IL-5 is the most important cytokine for eosinophil differentiation and activation in asthma." (PMID 38785953, 2024). "Mepolizumab and reslizumab, monoclonal antibodies that target IL-5, are used to treat asthma." (PMID 38534377, 2024). "This nuanced understanding of sFcεRI dynamics offers potential insights into the immunomodulatory effects of IL-5 targeted therapies in asthma, highlighting not only the direct impact on eosinophil viability but also its broader implications for the patient’s immunological landscape." (PMID 39001236, 2024). "Cytokines such as IL-5, implicated in asthma pathogenesis, are not recognized as potent pyrogens and are thus unlikely to precipitate fever in asthma patients." (PMID 38308249, 2024). "However, severe asthma can remain uncontrolled and requires add-on treatments such as mAbs directly targeting Th2 cytokines IL-4, IL-5 as well as their receptors." (PMID 38566968, 2024). "The results show that asthma is significantly correlated with elevated levels of IL-5 and IL-9 [IL-5, odds ratio (OR) = 1.112, 95% confidence interval (CI): 1.009–1.224, P = 0.032; IL-9, OR = 1.111, 95% CI: 1.013–1.219, P = 0.025], and the results of IVW are also supported by Radial-MR." (PMID 39175819, 2024). "Though data is limited at present, a study of 58 adult-onset asthma subjects prescribed anti-IL-5 therapy (N = 29 mepolizumab, N= 16 reslizumab, and N = 6 benralizumab) demonstrated a mean reduction in BMI by 1.0 ± 3.4 in the overall cohort and by 1.7 ± 3.8 in the obese group." (PMID 39200943, 2024). "However, even with as effective results as the asthma therapy reveals, the outcome of using anti-IL-5 in AD has remained almost unchanged since the study from 2005 in this field." (PMID 39062104, 2024). "Similarly, in asthma, viral infections trigger robust immune responses characterized by eosinophilic inflammation and the production of Th2 cytokines, including IL-4, IL-5, and IL-13." (PMID 39458339, 2024). "Also, at high dosages, tiotropium decreased the total number of inflammatory cells, including macrophages and eosinophils, and the levels of transforming growth factor-β1, IL-4, IL-5, and IL-13 in bronchoalveolar lavage fluid in a mouse model of asthma." (PMID 38419021, 2024). "Regarding the EWAS of BDR, the gene-set enrichment analysis revealed enrichment in several pathways relevant to asthma, including IL-5 (FDR = 1.1 × 10−2), IL-2 (FDR = 4.2 × 10−2), Fc epsilon Receptor I signaling pathways (FDR = 3.3 × 10−2), and cellular aging (FDR = 4.2 × 10−2)." (PMID 36979655, 2023). "Further future studies are needed to assess the promise of IL-5 antagonists in EETs with asthma." (PMID 37752512, 2023). "Moreover, high concentrations of IL-5 and eotaxins were observed in induced sputum taken from subjects manifesting acute asthma exacerbations." (PMID 37240477, 2023). "T2 airway inflammation in patients with asthma, although occurring along a continuum, is characterized by a specific set of cytokines, including IL-4, IL-5, IL-13, and the so-called alarmins, IL-25 and IL-33, and thymic stromal lymphopoietin (TSLP), secreted by activated epithelial cells." (PMID 37947596, 2023).
asthma (continued). "Neonatal hyperoxia exposure promotes the development of asthma-like features including large infiltration of inflammatory cells around the bronchi, increased airway eosinophilia, and upregulated expression of the type 2 cytokines IL-5 and IL-13." (PMID 37485534, 2023). "Interestingly, our model of asthma using endobronchial challenges demonstrated that IL-5 shows different kinetics of release compared with chemokines." (PMID 37259416, 2023). "Additionally, it was also observed that the proportions of CD3-CD56+CD16+ NK cells in asthma patients with AURVIs had a positive correlation with the IFN-γ/IL-5 ratios on day 1 and day 3, respectively." (PMID 37865742, 2023). "The anti-interleukin-5 (IL-5) monoclonal antibody mepolizumab and the anti-IL-5 receptor α (IL-5Rα) monoclonal antibody benralizumab, both available in Japan, deplete eosinophils by binding to IL-5 or IL-5Rα, thus ameliorating eosinophilic inflammation of the airways in asthma patients." (PMID 37629217, 2023). "In addition to being used as an add-on therapy in adults with severe uncontrolled asthma with an eosinophilic phenotype, this anti-IL-5 was also employed for patients with severe corticosteroid-dependent asthma." (PMID 36675006, 2023). "Among biologic agents, omalizumab helps reduce the frequency and severity of asthma attacks by binding to immunoglobulin E (IgE), while mepolizumab and reslizumab are monoclonal antibodies that target interleukin-5 (IL-5) and are used to treat severe eosinophilic asthma." (PMID 37353829, 2023). "Interestingly, we observed elevated frequencies of IFNγ+IL-5+, IFNγ+IL-9+, and IFNγ+IL-13+ double-producing Tc cells, supporting type-2 skewing of IFNγ+ Tc1 cells in asthma." (PMID 37612281, 2023). "Notably, IL-5 is known to play a major role in promoting eosinophil recruitment and promote the progression of allergy or asthma." (PMID 37193606, 2023). "The introduction of IL-5 targeting treatment in neoplastic or idiopathic hypereosinophilia mirrors the increasing interest in recent years in mABs targeting the IL-5 pathway for the treatment of hypereosinophilic conditions such as severe asthma and EGPA." (PMID 37274287, 2023). "The first randomized controlled trial (phase IIa) assessed the effect of a single intravenous infusion of the first anti-IL-5 monoclonal antibody [SB-240563] on the airway status after a challenge with an inhaled allergen in unselected patients with mild asthma conducted in 2000." (PMID 36982789, 2023). "Cytokines such as IL-4, IL-5, IL-9 and IL-13 and their receptors have been chosen as targets for monoclonal antibody-based treatments due to their importance in the pathogenesis of asthma." (PMID 37334374, 2023). "Thus, type 2 cytokines, such as IL-4, IL-5, and IL-13, are promising therapeutical targets for AR and also other allergic diseases, such as asthma and atopic dermatitis." (PMID 37109185, 2023). "In addition to IL‐4 and IL‐5, granulocyte‐macrophage colony‐stimulating factor (GM‐CSF) is also an important mediator driving eosinophil accumulation in airway inflammation in asthma." (PMID 37773696, 2023). "Comparing effectiveness on asthma outcome parameters of anti-IL5/IL5R." (PMID 38033455, 2023). "However, the effectiveness of IL-5 biologics in eosinophilic COPD patients was found to be worse than in asthma." (PMID 37371101, 2023). "Moreover, the anti-IL-5 antibody mepolizumab, already approved for asthma, has been the first drug specifically approved for the treatment of EGPA due to its inhibitory effect on various functions of eosinophils." (PMID 36975372, 2023). "To date, the United States Food and Drug Administration (FDA) has approved six biologics for use in selected severe asthma patients: Omalizumab (anti-IgE); Mepolizumab, Benralizumab, Reslizumab (anti-IL5/anti-IL5Rα); Dupilumab (anti-IL4Rα); and Tezepelumab (anti-TSLP)." (PMID 38259298, 2023). "Main findings of studies comparing BMI on IL-5/IL-5Rα biologic response in severe asthma patients." (PMID 38259298, 2023).
asthma (continued). "At present, treatment with anti-IL5/anti-IL5Rα agents in asthma is initiated according to eosinophil counts and other factors, yet it is possible that a more proximal factor may be an even better predictor of drug response." (PMID 35537820, 2023). "In asthma, T helper type 2 (Th2) cells, basophils, or mast cells were a source of IL‐4 and IL‐5." (PMID 37773696, 2023). "Additionally, we analyzed and compared the key BPs between DEP and APM exposure, focusing on asthma because asthmatic features, including eosinophil infiltration and increased IL-5 production, were significantly enhanced in the BALF of the APM group." (PMID 37045933, 2023). "In this sense, it has been confirmed that G-1 possesses encouraging therapeutic potential for asthma treatment, since it diminished airway hyperresponsiveness and inflammation (decrease in IL-5 and IL-13 levels in bronchoalveolar lavage fluid) in asthma models." (PMID 37895016, 2023). "Drugs targeting the IL-5/R axis are among the most widely used therapies for asthma treatment." (PMID 37163370, 2023). "However, during asthma, Th2 cytokines such as IL-5 can induce prolonged eosinophil survival, activation, and trafficking to the site of injury." (PMID 37063828, 2023). "Decreasing the Th2-associated cytokines IL-4, IL-5, and IL-13, and increasing the Th1 cytokine IFN-γ may help to alleviate the inflammatory response in asthma." (PMID 36846048, 2023). "IL-5 plays a more central role in the pathogenesis of type 2-high asthma." (PMID 37265457, 2023). "Therefore, we have in this study examined the relationship between the presence of bronchiectasis in severe asthma, the level of eosinophilic airway inflammation and degranulation, as well as activation of inflammatory pathways relating to IL-5 and IL-4/13." (PMID 37780108, 2023). "Type 2 inflammation occurs in approximately 70% of severe asthma patients and is promoted by a broad network of hyper-expressed cytokines, namely IL-4, IL-5, IL-13, and several immune cells, including mastocytes, type-2 helper lymphocytes, type-2 innate lymphoid cells, basophils, and eosinophils." (PMID 37298514, 2023). "Microbial differences in asthmatics have an impact on the production of mucins and inflammatory factors, for example, interleukin (IL)-4 and IL-5, and alterations in gut microbial patterns are closely related to the degree of sensitization and inflammation in asthma." (PMID 36636604, 2023). "Another biologic agent on IL-5, benralizumab, a monoclonal antibody directed against the alpha subunit of the IL-5R, has also shown significant clinically relevant benefits in patients with severe asthma." (PMID 37377958, 2023). "Furthermore, an increased proportion of IL‐5+ILC2s and IL‐13+ILC2s was observed in PBMCs of patients with asthma, particularly in the EA group." (PMID 37357549, 2023). "The use of anti-IgE and anti-IL5 may even protect asthma patients from the risks of viral-induced exacerbations." (PMID 35155689, 2022). "Examples of pathways or networks that are implicated by GWASs in asthma are the IL33-IL1-RL1 receptor pathway, leading to eosinophilia, and the T-helper-2 (Th2) cytokine IL-5 and IL-4RA receptor, leading to eosinophilia and type 2 inflammation or viral response (CDHR3, ORMDL3)." (PMID 35656293, 2022). "Indeed, both the cytokines IL-4 and IL-5 as well as IL-13 were augmented in asthma mice, while the level of anti-inflammatory cytokines IL-2, IFN-ɣ, and IL-10 were drastically reduced." (PMID 36685604, 2022). "Toxocara infection modulates the immune response to Th2 and the secretion of IL4, IL5, and IL13, which could theoretically be associated with asthma." (PMID 36250067, 2022). "Contoli M, Papi A. Effects of anti-IL-5 on virus-induced exacerbation in asthma." (PMID 35313976, 2022). "In asthma, eosinophils induce the activation of Th2 and express IL-5 in conjunction with basophils." (PMID 35878202, 2022).
asthma (continued). "In the study on treatment of asthma, it can diminish the expression of IL-4, IL-5, IL-13, IL-17A, IgE, CCL5, and CCL11, inhibit NF-kB- and JNK-mediated inflammatory signaling, and reduce oxidative damage through decreasing the activity of ROS and increasing SOD." (PMID 36588723, 2022). "IL-5 promotes eosinophilic inflammation in the pathogenesis of asthma." (PMID 36499236, 2022). "The concentration of IL-5 (type-2-related marker) was used as a primary parameter relating the current findings to the past research and allowing the assignment to CRS phenotypes (CRSwNP/CRSsNP) and associated diseases (asthma, N-ERD, and allergies)." (PMID 35455762, 2022). "Biologic drugs, such as anti-IgE and anti-IL-5, anti-IL-4/IL-13 monoclonal antibodies, are currently being used with clinical success in patients with type-2 diseases, such as asthma and CRSwNP, and only recently some authors suggested their efficacy also in the treatment of comorbid EOM." (PMID 35207196, 2022). "Sabogal Piñeros YS, Bal SM, van de Pol MA, Dierdorp BS, Dekker T, Dijkhuis A, Brinkman P, van der Sluijs KF, Zwinderman AH, Majoor CJ, Bonta PI, Ravanetti L, Sterk PJ, Lutter R. Anti-IL-5 in mild asthma alters rhinovirus-induced macrophage, B-cell, and neutrophil responses." (PMID 35313976, 2022). "Asthma and associated type 2 inflammation are driven by both the innate (type 2 innate lymphoid cells) and adaptive [T helper type 2 (Th2) cells] immune systems, characterized by the release of cytokines such as interleukin (IL)-4, IL-5, and IL-13, key pathophysiologic characteristics of asthma." (PMID 35371026, 2022). "Furthermore, the release of IL-4, IL-5, and IL-13 play a central role in the initiation and development of chronic airway inflammation of asthma." (PMID 36213326, 2022). "Since eosinophilic inflammation represents a specific endotype in asthma and other Th2-driven diseases, mAbs targeting IL-5 (mepolizumab and reslizumab) or IL-5R (benralizumab) have been successfully tested to treat severe refractory eosinophilic asthma, representing a therapeutic option." (PMID 35956071, 2022). "Targeting IL-5 and IL-6 pathways are research hotspots in the treatment of asthma." (PMID 36520525, 2022). "Immunoglobulin E (IgE), interleukin-5 (IL-5) and its receptors, and interleukin-4 (IL-4) receptors are used as molecular targets for clinical diagnosis of asthma; however, specific and individual differences are very large, and the clinical treatment of asthma patients is still inadequate." (PMID 36213574, 2022). "IL-5 is the primary regulator of eosinophil proliferation, migration, activation and survival and it also affects the function of mast cells and basophils, becoming one of the main pharmacological targets in severe asthma." (PMID 35455709, 2022). "In a longitudinal study of people with severe asthma receiving the anti-IL-5 monoclonal antibody mepolizumab, elevated serum CRP was a marker of non-eosinophilic exacerbations associated with infections, although these were viral rather than bacterial infections in the majority of cases." (PMID 36130784, 2022). "Therefore, there remains scope for further research targeting the IL-5 pathway for asthma therapeutics." (PMID 36232470, 2022). "Given that anti-IL5 therapy had limited impact on eosinophil recruitment and asthma exacerbations, there might be a potential alternative mechanism of eosinophil infiltration." (PMID 35958620, 2022). "Seven hypermethylated (CCL11, TNF, IL5, CCL2, CXCL1, CCL8, IL17RB) mRNAs (>twofold compared with control) were finally selected, as their mRNAs have been clearly reported as being associated with asthma." (PMID 36250525, 2022). "GLA could regulate the Th1/Th2 balance; increase the IL-12 level; decrease the IL-4, IL-5, and IL-13 levels; and inhibit the inflammatory responses in asthma." (PMID 35859797, 2022).
asthma (continued). "Type 2 innate lymphoid cells (ILC2), type 2 T-helper (Th2) cells, and related cytokines (such as IL-4, IL-5, and IL-13) are major players in the pathological changes and clinical symptoms of asthma, and increasing attention has been paid to anti-IL-5, anti-IL-5Rα, and anti-IL-4Rα therapy." (PMID 36530558, 2022). "Moreover, all responders completely stopped with their OCS maintenance therapy, and all of the patients who were nonresponders had to continue with their OCS due to uncontrolled asthma, despite anti-IL-5 treatment." (PMID 35055384, 2022). "Th2-predominant inflammation associated with high levels of IL-5 and eosinophils is evident in the majority of patients with severe asthma and nasal polyps but definitely not in all of them." (PMID 35743760, 2022). "In spite of similar tissue cellular inflammation, sputum IL‐4, IL‐5 and CCL26 were increased in T2‐high versus T2‐low asthma, and several further T2‐associated cytokines, PGD2 and LTE4, were increased in T2‐high and T2‐intermediate asthma compared with healthy controls." (PMID 35579040, 2022). "TH2-high asthma is characterized by allergic sensitization and eosinophilic inflammation of the respiratory tract, guided by type 2 prototypical cytokines comprising IL-4, IL-5 and IL-13." (PMID 35743783, 2022). "Whereas Imuno TF reduced IL-4, IL-5, and IL-13 in lung and serum of asthma mice, we tested if this agent could modulate the gene expression of allergic asthma-associated transcription factors." (PMID 36685604, 2022). "For instance, the activation of T helper cells (Th) residing in the lungs, such as Th2 and Th17, promotes the inflammation, mucous secretion, and remodeling of the airway in asthma via the secretion of different cytokines, such as IL-4, IL-5, IL-13, and IL-17, and interferon-γ (IFN-γ)." (PMID 35888038, 2022). "IL-5 plays a pivotal role in the proliferation, migration and release of cytokines from eosinophils, therefore labelling it as a prime target for therapeutic intervention, specifically for the treatment of T2-asthma patients." (PMID 36232470, 2022). "Literature data demonstrated that anti-IL-5 monoclonal antibodies may improve not only symptoms, but also the QoL of severe asthma, ECRS, and EOM." (PMID 35207196, 2022). "In asthma, Naive T lymphocytes are inadequately prepared to respond to inhaled aeroallergens with Th2 polarity, and upon restimulation by inhaled aeroallergens, they produce Th2 cytokines, IL-4, IL-5 and IL-13, that promote the pathological mechanisms of asthma." (PMID 35745177, 2022). "A clinical study demonstrated that a greater number of IL-13-producing T cells and IL-17A-producing CD4+ memory T cells and an increased proportion of IL-5-producing ILC2s are present in the peripheral blood of female patients with asthma compared to those in the peripheral blood of male patients." (PMID 35625578, 2022). "The inflammatory cascade in severe asthma is mainly caused by T-helper 2 cells (Th-2) activation and the release of Th-2 related cytokines, predominantly Interleukin-4 (IL-4), IL-5, and IL-13.32,34 The extent of expression of these cytokines correlates with asthma severity." (PMID 35414610, 2022). "T helper cells type 2 (Th2), another subset of T lymphocytes, is essential in the process of asthma, secreting CKs such as IL-4, IL-5, and IL-13 that directly impair lung tissue or indirectly facilitate the proliferation of IgE-generating B cells and EOS, contributing to AHR and airway remodeling." (PMID 35812246, 2022). "The increased local IgE in nasal polyp tissue is correlated with increased Eosinophil cationic protein (ECP), IL-5, eosinophilic infiltration, and the presence of staphylococcal enterotoxin(SE)-IgE and asthma comorbidity, implicating the role of IgE in the mediation of T2 inflammation." (PMID 36159836, 2022). "However, in contrast, enhanced synthesis of pro-inflammatory cytokines in asthma, such as IL-4, IL-5, IL-13, and IL-33, can contribute towards maintaining the lean state." (PMID 35807067, 2022).